PGR (progesterone receptor)
Diseases named in the same sentence as PGR in open-access papers (continued):
Sharing a sentence is not in itself a finding about the gene and the disease.
tumor (continued). "On the basis of these data, we therefore sought to explore the effects of sirolimus and sunitinib treated of NMU induced tumors on the tumor growth, histological changes, and protein expressions of ER, PgR and HER2." (PMID 33112549, 2020). "RU486 (mifepristone), a glucocorticoid and progesterone receptor antagonist, has been reported to exert antiproliferative effects on tumor cells." (PMID 33053110, 2020). "The prognostic stage incorporates the biological factors, such as the tumor grade, ER and PgR expression and HER2 overexpression and/or amplification." (PMID 32472474, 2020). "Axillary lymph involvement, number, tumor size, estrogen receptor, progesterone receptor, and cerb-B2 status are safe markers that can be used to determine prognosis in our series." (PMID 32754412, 2020). "It is based on certain biomarkers such as blood presser, dimension of tumor, Progesterone Receptor and Estrogen Receptor status of tumor." (PMID 34171941, 2020). "In this study, it was proved that anti-tumor treatment potentially preventing the estrogen dependent mechanism towards cancer cells progression and lowered the ER and PgR expression." (PMID 33112549, 2020). "Multiple logistic regression analysis, adjusted for clinical characteristics and tumor properties, suggested a regression model including miR-4480 and PgR." (PMID 31603918, 2019). "Compared to general population, in the current series we found a higher percentage of Her2 + tumours (24.5% vs 13–15%1) and triple negative tumours (16.3% vs 11.2%17), whereas the incidence of ER/PgR + tumours was similar (77.6% vs 80%)." (PMID 31645624, 2019). "OSbrca implanted a selective set of clinical parameters, including tumor grade, age, status of ER/PgR/HER2, menopause status, and so on." (PMID 31921624, 2019). "The estrogen receptor/progesterone receptor (ER/PR) status of CTCs was compared to that of the primary tumor in several studies." (PMID 31330794, 2019). "Histologic review of each PDX was performed, primarily to determine how closely each tumor matched the original patient tumor in terms of morphology and immunohistochemical staining patterns for estrogen receptor, progesterone receptor, HER2, and Ki67." (PMID 31231469, 2019). "Traditionally, tumours are classified according to the presence of oestrogen receptors (ER), progesterone receptors (PgR) (considered together as hormone receptor status), and human epidermal growth factor receptor 2 (HER2)." (PMID 31769425, 2019). "High levels of LPCAT1 immunostaining were significantly linked to unfavorable tumor features including high pT stage, high BRE grade, estrogen and progesterone receptor negativity, and HER2 amplification (p<0.0001 each)." (PMID 31533087, 2019). "Principal conclusions: Tumor-associated MUC1 is a very important biomarker for breast cancer next to the traditional markers estrogen receptor (ER), progesterone receptor (PR) and HER/2-neu." (PMID 31588183, 2019). "These tumor cells stained negatively for estrogen receptor (ER), progesterone receptor (PgR), and human epidermal growth factor receptor 2 (HER2)." (PMID 31076887, 2019). "Immunohistochemistry showed epithelial membrane antigen positivity, anti-pancytokeratin 1 markers of tumor cells positivity, chromogranin A negativity, actin negativity, S100 negativity, estrogen receptor negativity, and progesterone receptor negativity." (PMID 31151475, 2019). "The clinicopathological findings of the 27 patients with the initial results of ER−/PgR+ were as follows: the patients’ ages ranged from 39 to 73 years (mean age 55.8 years), and tumor size ranged from 0.1 to 11.7 cm (mean size 1.8 cm)." (PMID 30066060, 2019). "Most tumours were also positive for progesterone receptor with slightly different frequencies: 72 and 60% for groups A and B, respectively (P = 0.094)." (PMID 30990940, 2019).
tumor (continued). "Now, with data showing progesterone inhibition of tumor growth, it makes it reasonable to perform more detailed mechanistic studies to help define the interaction of nuclear progesterone receptor with nuclear FoxO1 activity in GBM." (PMID 30700763, 2019). "In cohort A, 8.1% patients were PD-L1-positive; PD-L1 positivity showed a correlation with high degree of tumor-infiltrating lymphocytes (TILs), estrogen receptor negativity, progesterone receptor negativity, and high histological grade." (PMID 31723167, 2019). "First, as a control, we show that as expected oestrogen receptor alpha (ESR1) and progesterone receptor (PGR) were significantly different between these groups, with median expression in ER-negative tumours dramatically lower than in ER-positive tumours." (PMID 31683867, 2019). "An important clinical difference is that in GeparTrio, hormone receptor positivity was defined as ≥ 10% of tumor cells stained for estrogen or progesterone receptor, in the MD Anderson cohort, as any stained tumor cells." (PMID 31829264, 2019). "The change in AvProg showed a borderline significant correlation with PGR expression (r = 0.34, p = 0.06), such that the tumours with higher PGR expression showed a greater change in AvProg." (PMID 31754627, 2019). "Cluster D was enriched for tumour samples taken in W2 (25% W1, 45% W2, 30% W3) and showed the highest relative expression of PAGs and the lowest of PRGs and PGR (30% IHC PgR −ve)." (PMID 31754627, 2019). "We considered 159 BC patients with available primary tumor samples and data on AR and ER expression, of whom 125 patients had luminal tumor (defined as ER ≥1% and/or PgR ≥1% with any Ki67 or HER2 values)." (PMID 31110518, 2019). "This analysis confirmed that the following factors have prognostic value: liver metastases, bone-only disease, tumor grade, progesterone receptor (PR) expression, and ECOG performance status." (PMID 30959874, 2019). "We analyzed the Spearman correlation between the number of mutations attributed to each of the signatures and five different clinical/demographic features: age, tumor grade, final estrogen-receptor (ER), progesterone-receptor (PR), and HER2 status." (PMID 31349863, 2019). "In our seven re-evaluated and confirmed as ER−/PgR+ cases, the staining proportions of tumor cells were 0% in ER and 1–69% (average 15.8%) in PgR." (PMID 30066060, 2019). "The overexpression of several sex hormone receptors, in particular, estrogen receptor alpha (ERα), progesterone receptor (PgR), and androgen receptor (AR), suggests their fundamental role in tumor pathogenesis and progression." (PMID 29385707, 2018). "The traditional classification of BC has utilised tumour morphology and assessment of oestrogen receptor [ER], progesterone receptor [PR] and human epidermal growth factor receptor 2 (HER2) expression." (PMID 29532008, 2018). "Among BRCA1m carriers, 22% of tumours were ER-positive and 21% were PgR-positive, and among BRCA2m carriers, 77% were ER-positive and 64% were PgR-positive." (PMID 29867226, 2018). "Immune-modulated histomorphological changes in LNs can be summarized into subtype-independent groups (pT and pN) and subtype-dependent groups (tumor grade, estrogen and progesterone receptor protein expression)." (PMID 29593307, 2018). "They found that the switch from migration to proliferation was regulated by increased HER2 expression and tumour-cell density involving microRNA-mediated progesterone receptor down-regulation." (PMID 29865880, 2018). "Individual patient prognosis depends on the status of biological markers in the primary tumor including the estrogen receptor (ER), progesterone receptor (PR), human epidermal growth factor receptor 2 (HER2), and Ki671,2." (PMID 29321587, 2018).
tumor (continued). "Meanwhile, women with ER−/PGR+ or ER-poor/PGR− tumours also receive adjuvant anti-oestrogen hormone therapy with hope that this treatment will benefit this group of patients." (PMID 29986702, 2018). "The pan-hormonal action of steroid hormonal receptors, including estrogen receptor alpha (ERα), androgen receptor (AR), progesterone receptor (PR), and glucocorticoid receptor (GR) in this understudied tumor type remains wholly unexamined." (PMID 29396493, 2018). "Multivariate analysis with Cox regression showed that grade (P < 0.001), tumor size (P < 0.001), and progesterone receptor status (P < 0.001) were independent prognostic factors for OS." (PMID 29416621, 2018). "Of the 810 HR+ patients (ER+ and/or progesterone receptor-positive [PgR+]) with tumor blocks available, 530 were formalin fixed and eligible for the RS assessment." (PMID 29728098, 2018). "Expression of cVEGFR1 was statistically prevalent in invasive tumor phenotype (p = 0.041) and PgR-positive expression (p = 0.009)." (PMID 29716631, 2018). "Tumors originating in F344 display high inter- and intra-tumor heterogeneity in terms of estrogen receptor (ER) and progesterone receptor (PR) expression, as observed in women, with the majority being ER+PR+." (PMID 30096949, 2018). "Current clinical guidelines recommend tumour biomarkers (ER, PgR, HER2, Oncotype DX, Endo Predict, PAM50), pathological features (eg: TNM staging system) and risk stratification tools." (PMID 29385991, 2018). "Since the introduction of BC molecular classification, systemic therapies are tailored according to BC heterogeneity (biomarkers as ER/PgR, Her2, Ki67) and aggressiveness (histological subtypes, histological grade, and tumor stage)." (PMID 29675397, 2018). "Previous studies highlighted associations between tumor proliferation and a variety of clinico-pathological endpoints, such as tumor grade, stage, and ER/PgR expression." (PMID 29304138, 2018). "Tumor cells were reactive for estrogen receptor, progesterone receptor, desmin, alpha smooth muscle actin, and caldesmon." (PMID 30693147, 2018). "Ki67 indices also correlated positively with the Recurrence Scores, tumor grade and mitotic score, and negatively with ER and PgR Allred scores." (PMID 29304138, 2018). "In the present study, patients’ age, tumor size, grade and proliferation, and median levels of ER and PgR expression played a critical role in disease management and guided physicians and patients in therapeutic decision-making." (PMID 29348868, 2017). "Several studies have found that patients with ER- and/or PgR-positive BCLM are good candidates for liver metastasectomy due to favorable tumor biology and administration of hormone therapy." (PMID 28220470, 2017). "Sixty per cent of the tumours from this cohort were positive for ER and PgR, which is a clinical indicator of ER function." (PMID 28510570, 2017). "Most tumours were hormone receptor positive: 91% were estrogen receptor (ER) positive and 81% progesterone receptor (PR) positive." (PMID 28874143, 2017). "Clinicopathological variables, such as ER status, PgR status, age and tumor size, measured at diagnosis, were obtained from patient records." (PMID 28122498, 2017). "After mastectomy, the findings of an additional immunohistochemical analysis of the tumor were as follows: estrogen receptor (ER (slightly +)), progesterone receptor (PR (slightly +)), and human epidermal growth factor receptor 2 (HER2 (1+))." (PMID 28662703, 2017). "The items matched were patient's age, tumor size category, histological grade, PgR expression, using a cut off of 20%, and Ki67 index, as a continuous variable." (PMID 29348868, 2017). "The presence of ER and PgR on tumor cells at the time of surgery guides adjuvant therapy, as an important predictor of both prognosis and hormone dependency." (PMID 28356061, 2017). "MATV (HR = 1.01, P < 0.01), progesterone receptor expression (HR = 2.90, P = 0.03) and tumor histology (HR = 3.80, P = 0.02)." (PMID 28057031, 2017).
tumor (continued). "Three parameters remained significantly associated with EFS in multivariate analysis: MATV (HR = 1.01, P < 0.01), progesterone receptor expression (HR = 2.90, P = 0.03) and tumor histology (HR = 3.80, P = 0.02)." (PMID 28057031, 2017). "FSTL3 expression was classified semiquantitatively and tested for possible correlation with age, menopause status, stage, tumor histological type and grade, estrogen receptor, progesterone receptor, and HER2 expression." (PMID 28178680, 2017). "Immunohistochemical staining of the vulvar specimen showed the tumor cells to be 100% estrogen-receptor-positive, 100% progesterone-receptor-positive, human epidermal growth factor 2-negative, and gross cystic disease fluid protein 15 (GCDFP-15)-positive." (PMID 28510222, 2017). "The most important molecular tumor characteristics include estrogen receptor (ER), progesterone receptor (PR), and human epidermal growth factor receptor 2 (HER2) expression." (PMID 28134770, 2017). "The expression of ER and PgR was correlated with the age of the patients (p = 0.026) and the tumor grade (p = 0.0004)." (PMID 28173783, 2017). "The only discordant case was HER2- by both, IHC and FISH, and corresponded to an ER+/PgR+ tumor with a proliferation index (Ki67) of 20%, and was classified as high-risk by both tests, MP and EP." (PMID 28886093, 2017). "In the per protocol analysis, all patients entered had strongly ER-positive tumours (Allred ≥ 7), 62% were strongly PgR positive (Allred ≥ 7) and 50% were HER2 positive." (PMID 28795252, 2017). "These researchers showed a gene body hypomethylation signature that was exclusively associated with the basal-like subtype, a high-grade subgroup of tumours characterized by negativity for the ER, PgR and HER2 expression and related to a poor prognosis." (PMID 29259228, 2017). "Estrogen receptor and progesterone receptor have been found to be more expressed in grade 1 tumours than grade 3 tumours." (PMID 29187928, 2017). "Both the tumours had oestrogen and progesterone receptor positive and human epidermal growth factor receptor 2 negative statuses." (PMID 28738860, 2017). "The selected features were diagnosis age, tumor size, lymph node involvement ratio, number of involved axillary lymph nodes, progesterone receptor expression, having hormone therapy and type of surgery." (PMID 28018557, 2017). "Age, tumor size, tumor grade, Ki67, ER and PgR expression differed significantly between the two cohorts." (PMID 29348868, 2017). "A correlation was found between the ER/PgR and the tumor grade, which corroborates with the literature data." (PMID 28173783, 2017). "Of the 88 patients 53 (60.2%) had oestrogen receptor (ER)-positive tumours, whereas 34 (38.6%) had progesterone receptor (PR)-positive tumours." (PMID 28750640, 2017). "A strong inverse correlation was found between nuclear BAG-1 expression and tumour size, whereas ERα and PgR expression moderately correlated with nuclear and (to a lesser extent) with cytplasmic BAG-1 expression." (PMID 28510570, 2017). "When using continuous data, univariate Cox regression analysis showed that tumor size (p=0.011) and Ki67 index (p=0.028) were significantly associated with poor DFS, while ER (p=0.016), PgR (p=0.045) and Ki67 index (p=0.012) were associated with OS." (PMID 29029467, 2017). "The distribution of RS varied significantly according to different tumor grade, T stage, progesterone receptor(PR) status, Ki67 index and molecular subtypes (p<0.05)." (PMID 28404972, 2017). "Stratification of samples analyzed in this study according to tumor subtype, grade, and ER, PgR, and HER2 status." (PMID 28145100, 2017). "There is a high incidence of oestrogen (ER) and progesterone receptor (PR) expression, and evidence that these tumours are hormonally responsive." (PMID 27891213, 2016). "Immunohistochemical stains were performed on 92 tissue blocks of PTC for estrogen receptor (ER) and progesterone receptor (PR) expression in tumor cells." (PMID 27757203, 2016).